CA5A (carbonic anhydrase 5A)
Description:
Mitochondrial carbonic anhydrase that catalyzes the reversible conversion of carbon dioxide to bicarbonate/HCO3. Mitochondria are impermeable to HCO3, and thus this intramitochondrial carbonic anhydrase is pivotal in providing HCO3 for multiple mitochondrial enzymes that catalyze the formation of essential metabolites of intermediary metabolism in the urea and Krebs cycles.
Synonyms: CA5; CAV; CAVA; CA5AD; GS1-21A4.1
Tractability: Small molecule: an approved drug acts on it; a high-quality ligand is known; it belongs to a druggable protein family. PROTAC: ubiquitination databases record sites on it; its protein half-life has been measured; a small molecule that binds it is known.
Target class: Enzyme; Lyase
Gene: Protein-coding gene on chromosome 16 (87,881,546 to 87,936,580, reverse strand). Ensembl gene ENSG00000174990.
Subcellular location: Mitochondrion
Pathways (Reactome):
Metabolism: Reversible hydration of carbon dioxide
Gene Ontology:
Molecular function: carbonate dehydratase activity; zinc ion binding
Cellular component: mitochondrion; cytoplasm; mitochondrial matrix
Genetic constraint (gnomAD): Loss-of-function variants: 22 observed, 25 expected, observed/expected ratio (o/e) 0.88, 90% interval 0.63 to 1.26. The upper end of that interval is the gene's LOEUF score, 1.26, which puts it in group 5 of 6, group 1 being the genes least tolerant of losing a copy. Missense variants: 372 observed, 306.35 expected, observed/expected ratio (o/e) 1.21, 90% interval 1.12 to 1.32. Synonymous variants: 140 observed, 118.86 expected, observed/expected ratio (o/e) 1.18, 90% interval 1.03 to 1.36.
Gene-disease validity (ClinGen):
ClinGen rates the evidence that CA5A causes each of these diseases.
hyperammonemic encephalopathy due to carbonic anhydrase VA deficiency (autosomal recessive): Definitive.
Homologues: Orthologues: chimpanzee CA5A (98% identical), macaque CA5A (83% identical), dog CA5A (74% identical), mouse Car5a (70% identical), pig CA5A (70% identical), rat Car5a (70% identical), guinea pig CA5A (63% identical), zebrafish ca2 (43% identical), Caenorhabditis elegans cah-5 (30% identical), Drosophila melanogaster CAH16 (27% identical), Drosophila melanogaster CARPB (27% identical), Drosophila melanogaster CAH6 (26% identical), and 10 more. Paralogues in human: CA5B (60% identical), CA2 (44% identical), CA7 (42% identical), CA1 (42% identical), CA13 (40% identical), CA3 (39% identical), CA8 (30% identical), CA14 (30% identical), CA6 (28% identical), CA10 (28% identical), CA12 (28% identical), CA9 (28% identical), and 2 more.
Diseases named in the same sentence as CA5A in open-access papers:
CA5A is named in the same sentence as 30 diseases in open-access papers, as found by Europe PMC text mining. Sharing a sentence is not in itself a finding about the gene and the disease. The quoted sentences say what the papers report.
Hyperammonemia (9 papers, 2019 to 2026). An increased concentration of ammonia in the blood. "Two unrelated Russian patients, who suffered from hyperammonemia due to carbonic anhydrase VA deficiency, have been reported recently; both these subjects were homozygous for CA5A c.555G>A p.(Lys185=) allele." (PMID 39273284, 2024). "Diseases associated with CA5A include carbonic anhydrase Va deficiency, hyperammonemia and carbonic anhydrase Va deficiency." (PMID 36428413, 2022). "Hyperammonemia due to carbonic anhydrase VA deficiency (OMIM# 615751) is a rare, life-threatening hereditary disease caused by biallelic mutations in the CA5A gene, presenting as encephalopathic hyperammonemia of unexplained origin during the neonatal period and infancy." (PMID 36499355, 2022). "Carbonic anhydrase VA (CA5A) deficiency (OMIM 615751) is an ultra-rare inborn error of metabolism, presenting in newborns, infants, and young children with a pentad of encephalopathy, hyperammonemia, lactic acidosis, ketonuria, and hypoglycemia." (PMID 42194994, 2026).
Obesity (5 papers, 2021 to 2025). Accumulation of substantial excess body fat. "CA5A encodes a carbonic anhydrase enzyme linked to various metabolic processes, including obesity-related pathways." (PMID 38528581, 2024). "Serum proteome analysis revealed the effects of the infection on circulating adiponectin, interleukin 6 (IL-6), and carbonic anhydrase 5A (CA5A), which are all related to obesity and blood glucose abnormalities." (PMID 38474155, 2024). "Due to its involvement in lipid metabolism, CA5A was proposed as a promising therapeutic target for novel anti-obesity pharmacological agents." (PMID 39062004, 2024). "Our in silico findings suggest that the potential anti-obesity and hypolipidemic activities of Cynarae extract, Crataegi extract, and Rosmarini extract could be partly supported by the inhibition of the hepatic CA5A by rosmarinic acid and chlorogenic acid." (PMID 39062004, 2024). "As obesity is a known risk factor for IIH, the connection between CA5A and IIH could indicate novel mechanistic pathways underlying this correlation." (PMID 38528581, 2024). "Interestingly, carbonic anhydrase 5A (CA5A) was shown to be involved in the hepatic synthesis of fatty acids and to be a promising therapeutic target for obesity management." (PMID 39062004, 2024). "Further studies are warranted to experimentally validate the predicted CA5A inhibitory activities of RA and CGA and to investigate the hypolipidemic and antioxidant activities of the proposed plant extracts in animal models of dyslipidemia and obesity." (PMID 39062004, 2024).
Hypoglycemia (3 papers, 2019 to 2026). A decreased concentration of glucose in the blood. "A CA5A gene mutation has been reported to cause infantile hyperammonemic encephalopathy, which includes hypoglycemia, hyperlactatemia, metabolic acidosis, and respiratory alkalosis." (PMID 38474155, 2024).
acute myocardial infarction (1 paper, 2024). Necrosis of the myocardium, as a result of interruption of the blood supply to the area. "CA5A levels are strongly associated with unstable angina and acute myocardial infarction, but without suggesting that it is due to up- or downregulation." (PMID 38474155, 2024).
COVID-19 (1 paper, 2024). A disease caused by infection with severe acute respiratory syndrome coronavirus 2. "COVID-19 has been frequently associated with blood glucose abnormalities, which may be reflected by altered serum CA5A expression." (PMID 38474155, 2024).
Organic aciduria (1 paper, 2025). "‘Secondary’ hyperammonaemia may be a feature in other metabolic disorders like organic acidurias (e.g. methylmalonic aciduria, propionic aciduria) or carbonic anhydrase 5A-deficiency (CA5A gene)." (PMID 40285952, 2025).
prediabetes (1 paper, 2024). "It has been shown that CA5A is related to hepatic glucose in T2D and higher levels of fasting glucose, and it therefore has been suggested as a new novel marker for prevalent prediabetes and T2D." (PMID 38474155, 2024).
cancer (4 papers, 2018 to 2023). A tumor composed of atypical neoplastic, often pleomorphic cells that invade other tissues. "The mitochondrial CA5A and CA5B show relatively similar expression levels across cancer epithelial cells, endothelial cells, cancer-associated fibroblasts, and immune cells (T cells, B cells, and myeloid cells)." (PMID 37098526, 2023). "Although few studies have shown expression of CA VA and CA VB in cancer, the TCGA database shows high expression of CA5A in an RNA sequence study performed with liver hepatocellular carcinoma patient samples." (PMID 29495652, 2018). "CA5B mRNA upregulation in cancer is more widespread than CA5A with highest expression observed in acute myeloid leukemia, prostate, and renal cell carcinomas." (PMID 29495652, 2018).
CA5A also shares sentences with these, for which no sentence is quoted: breast carcinoma (2 papers); infection (2); lactic acidosis (2); melanoma (2); developmental delay (1); dyslipidemia (1); Encephalopathy (1); epilepsy (1); heart failure (1); metabolic acidosis (1); metabolic disorders (1); metastatic melanoma (1); metastatic prostate carcinoma (1); Miscarriage (1); mitochondrial disease (1); Neurodevelopmental delay (1); organic acidemias (1); parathyroid carcinoma (1); prostate carcinoma (1); prostate hyperplasia (1); scleroderma (1); unstable angina (1).